NT5C1A (5'-nucleotidase, cytosolic IA)
Description:
Catalyzes the hydrolysis of ribonucleotide and deoxyribonucleotide monophosphates, releasing inorganic phosphate and the corresponding nucleoside. AMP is the major substrate but can also hydrolyze dCMP and IMP.
Synonyms: cN1A; cN-I; cN-IA; CN1; MGC119199; MGC119201; CNI
Tractability: No criterion of Open Targets' tractability assessment is met for any kind of drug.
Gene: Protein-coding gene on chromosome 1 (39,651,229 to 39,673,328, reverse strand). Ensembl gene ENSG00000116981.
Subcellular location: Cytoplasm
Pathways (Reactome):
Metabolism: Purine catabolism; Pyrimidine catabolism
Gene Ontology:
Molecular function: 5'-deoxynucleotidase activity; 5'-nucleotidase activity; magnesium ion binding; protein binding; nucleotide binding
Biological process: allantoin metabolic process; AMP catabolic process; dAMP catabolic process; dGMP catabolic process; IMP catabolic process; adenosine metabolic process; nucleoside metabolic process; nucleotide metabolic process
Cellular component: cytosol; cytoplasm
Genetic constraint (gnomAD): Loss-of-function variants: 19 observed, 29.92 expected, observed/expected ratio (o/e) 0.63, 90% interval 0.44 to 0.93. The upper end of that interval is the gene's LOEUF score, 0.93, which puts it in group 3 of 6, group 1 being the genes least tolerant of losing a copy. Missense variants: 393 observed, 428.37 expected, observed/expected ratio (o/e) 0.92, 90% interval 0.84 to 1. Synonymous variants: 148 observed, 170.1 expected, observed/expected ratio (o/e) 0.87, 90% interval 0.76 to 1.
Homologues: Orthologues: chimpanzee NT5C1A (99% identical), macaque NT5C1A (99% identical), mouse Nt5c1a (95% identical), dog NT5C1A (95% identical), pig NT5C1A (93% identical), guinea pig NT5C1A (89% identical), rat Nt5c1a (87% identical), rabbit NT5C1A (87% identical), tropical clawed frog nt5c1b (78% identical), zebrafish nt5c1ab (71% identical), zebrafish nt5c1aa (68% identical). Paralogues in human: NT5C1B (61% identical).
Diseases named in the same sentence as NT5C1A in open-access papers:
NT5C1A is named in the same sentence as 59 diseases in open-access papers, as found by Europe PMC text mining. Sharing a sentence is not in itself a finding about the gene and the disease. The quoted sentences say what the papers report.
inclusion body myositis (20 papers, 2016 to 2026). A slowly progressive degenerative inflammatory disorder of skeletal muscles characterized by late onset weakness of specific muscles and distinctive histopathological features. "Indeed, inclusion body myositis has sometimes been associated with intracellular auto-Abs targeting the cytosolic 5’-nucleotidase 1A (cN1A; NT5C1A), a protein expressed in the periphery by muscle cells and cardiomyocyte and in the CNS by some astrocytes and neurons." (PMID 39114659, 2024). "However, myopathy is the most common presentation of VCP-MSP and it is possible that some cases of VCP-MSP are misdiagnosed as sporadic inclusion body myositis based on reactivity to NT5C1A antibodies." (PMID 35741724, 2022). "Autoantibodies to cytosolic 5′-nucleotidase 1A (cN-1A; NT5C1A) have a high specificity when differentiating sporadic inclusion body myositis from polymyositis and dermatomyositis." (PMID 29922285, 2018). "In 2013, two independent research groups described a novel antibody in sporadic inclusion body myositis (IBM): anti-cytosolic 5′-nucleotidase 1A (anti-cN-1A; anti-NT5C1A)." (PMID 29922285, 2018). "Anti-cytosolic 5′-nucleotidase 1A (NT5C1A) autoantibodies, which are prevalent in adult patients with inclusion body myositis, were detected in 27% of a JIIM cohort, although not specifically, and associated with severe disease." (PMID 39334579, 2024).
myositis (19 papers, 2016 to 2026). "Despite the absence of any apparent adverse health effects of whole-body deletion of both NT5C1A and NTC2 in our mouse model, the presence of auto-antibodies against NT5C1A was linked to (dermato)myositis while its overexpression in pancreatic cancer was linked to chemotherapy resistance." (PMID 39947478, 2025). "Notably, the longest H-DNA sequence of 797 bp lies entirely within the NT5C1A (5′-Nucleotidase, Cytosolic IA), which is associated with Myositis." (PMID 40041207, 2025). "Since 2014, the Washington University neuromuscular clinical laboratory has included anti‐NT5C1A antibody testing in its myositis panel or as an isolated antibody test." (PMID 33556224, 2021). "A number of antibodies are also linked to an increased risk of dysphagia: NXP2, FHL-1, SAE, HMGCR, NT5c1A, SRP, TIF1y, OJ and myositis-specific or -associated autoantibodies in general." (PMID 32650400, 2020). "Among the nine patients who had calcinosis cutis, seven patients (anti‐NT5C1A antibody seropositive (n = 4) and anti‐NT5C1A antibody seronegative (n = 3)) were tested for anti‐NXP2 antibody and anti‐SAE antibody through myositis panel test." (PMID 33556224, 2021). "Anti‐NT5C1A antibody testing is a worthwhile addition to a myositis panel for initial assessments to eliminate noninflammatory muscle diseases from diagnoses." (PMID 33556224, 2021). "Although a systematic review of the SLE patients in our cohort for the presence of muscle weakness has not been done, only 2 had documented clinically apparent myositis and neither of these had anti-NT5c1A antibodies." (PMID 31024569, 2019). "Thus, in these myositis, anti‐NT5C1A antibody is not an indicator of disease severity." (PMID 33556224, 2021).
Sjögren’s syndrome (15 papers, 2016 to 2025). "Anti-NT5c1A has a moderate sensitivity, yet displays high specificity for IBM, although recent data showed presence of anti-NT5c1A also in other autoimmune conditions, particularly in systemic lupus erythematosus and Sjogren’s syndrome." (PMID 37007787, 2023).
autoimmune disease (12 papers, 2016 to 2025). A disorder resulting from loss of function or tissue destruction of an organ or multiple organs, arising from humoral or cellular immune responses of the individual to their own tissue constituents. "Anti-NT5c1A antibodies have been detected in the serum of IIM patients as well as other autoimmune diseases." (PMID 39890639, 2025). "This suggests that anti‐NT5C1A antibody can be detected in autoimmune diseases other than IBM, however, seropositivity for anti‐NT5C1A antibody in IIMs other than IBM has not been assessed within a large population." (PMID 33556224, 2021).
dermatomyositis (8 papers, 2015 to 2026). Dermatomyositis (DM) is a type of idiopathic inflammatory myopathy characterized by evocative skin lesions and symmetrical proximal muscle weakness. "Anti‐NT5C1A antibody seropositive dermatomyositis patients had a higher frequency of calcinosis cutis (55% vs. 8%; P < 0.01)." (PMID 33556224, 2021). "Interestingly, among patients with dermatomyositis, antisynthetase syndrome, and IMNM that had an associated malignancy, all were seronegative for anti‐NT5C1A antibody." (PMID 33556224, 2021). "Of 593 patients, anti‐NT5C1A antibody was found in 159/249 (64%) IBM, 11/53 (21%) dermatomyositis, 7/27 (26%) antisynthetase syndrome, 9/76 (12%) IMNM, 20/84 (24%) nonspecific myositis, and 6/104 (6%) noninflammatory muscle diseases patients." (PMID 33556224, 2021). "Among patients with dermatomyositis (n = 53), antisynthetase syndrome (n = 27), and IMNM (n = 76), 11 (21%), 7 (26%), and 9 (12%) patients were seropositive for anti‐NT5C1A antibody, respectively." (PMID 33556224, 2021). "Notably, anti‐NT5C1A antibody positivity was seen in IBM, antisynthetase syndrome, IMNM, and dermatomyositis." (PMID 33556224, 2021). "The relationship between seropositivity for anti‐NT5C1A antibody and other clinicopathologic features in IBM or dermatomyositis have been discussed and some report that seropositivity for anti‐NT5C1A antibody in IBM or juvenile myositis predict a more severe phenotype." (PMID 33556224, 2021). "Anti‐NT5C1A antibody seropositivity did not correlate with malignancy, interstitial lung disease, response to treatments in dermatomyositis, antisynthetase syndrome, and IMNM, or survival in IIMs." (PMID 33556224, 2021). "This is probably due to the nature of the disease course of IBM, which progresses more slowly than dermatomyositis, IMNM, and polymyositis and is not an anti-NT5c1A antibody-related feature." (PMID 37058449, 2023).
pancreatic cancer (3 papers, 2018 to 2025). "First, we evaluated the expression of NT5C1A, CDA and DCK in KPC mice and OTM by analyzing the expression of GME in bulk pancreatic cancer tissue." (PMID 38744194, 2024).
polymyositis (3 papers, 2016 to 2023). A rare idiopathic inflammatory myopathy characterized by symmetric proximal muscle weakness and elevated muscle enzymes. "This consistency suggests that anti-NT5c1A antibody testing may be helpful in distinguishing polymyositis from IBM when clinicopathological findings are not sufficient to differentiate between the two groups." (PMID 37058449, 2023).
inflammatory myopathies (6 papers, 2015 to 2024). "To explore the clinical significance of anti-cytosolic 5’-nucleoditase 1A (NT5c1A) antibody seropositivity in inflammatory myopathies, we measured anti-NT5c1A antibodies and analyzed their clinical features." (PMID 37058449, 2023). "Additionally, anti-NT5c1A autoantibodies were also detected in patients with other inflammatory myopathies or autoimmune diseases." (PMID 37058449, 2023). "Therefore, to understand the clinical utility of the anti-NT5c1A autoantibody in the diagnosis of IBM, we measured the anti-NT5c1A autoantibody in inflammatory myopathies and analyzed the clinicopathological features." (PMID 37058449, 2023). "Although anti-NT5c1A antibody is known to be associated with IBM, seropositivity has also been noted in non-IBM inflammatory myopathies, and is insufficient to have clinical significance by itself." (PMID 37058449, 2023).
tumor (6 papers, 2018 to 2025). "Nt5c1A was strongly expressed in all murine and human tumour cells, whereas the tumour microenvironment was largely devoid of Nt5c1A expression." (PMID 28077438, 2018). "Only for NT5C1A we observed a higher expression in normal pancreatic tissue compared to tumor tissue which could be explained by different expression of RNA and protein levels caused by post-transcriptional modifications." (PMID 38744194, 2024). "Consequently, overexpression of NT5C1A was found to confer gemcitabine resistance in PDA tumor cells and in tumor-bearing mice." (PMID 36571444, 2023). "In tumor cells, for instance, gemcitabine-metabolizing enzyme levels and activity such as CDA, dCK or Nt5c1A/Nt5c3 may explain the discrepancy between high hENT1 level and poor response to gemcitabine." (PMID 31752123, 2019).
cancer (5 papers, 2018 to 2025). A tumor composed of atypical neoplastic, often pleomorphic cells that invade other tissues. "Immunohistochemical analysis of the source tumors revealed strong positive staining for hENT1, CDA, DCK, and NT5C1A in the cancer cells, whereas minimal expression was detected in the stromal cells." (PMID 33287390, 2020). "Among these, only four genes were significantly downregulated in fibroblasts compared with cancer cells (Nt5c1A, Nt5c3, Rrm2 and Ent2)." (PMID 28077438, 2018). "Furthermore, the key gemcitabine regulators hENT1, DCK, CDA, and NT5C1A were expressed to varying degrees among the different cancer cells, whereas PSCs displayed overall significantly lower expression than the cancer cells." (PMID 33287390, 2020). "Expression analysis of the key enzymes that regulate gemcitabine uptake (hENT1) and intracellular metabolism (CDA, DCK, NT5C1A, and DCTD) was performed in cancer cells and PSCs by immunofluorescence and by western blot analysis using total cell lysates." (PMID 33287390, 2020). "In cancer cells, gemcitabine-induced cytotoxicity was significantly lower following knockdown of hENT1 and DCK, whereas knockdown of CDA and NT5C1A had no impact, highlighting the importance of a balanced expression of the key regulators of gemcitabine metabolism for treatment effects to occur." (PMID 33287390, 2020).
NT5C1A also shares sentences with these, for which no sentence is quoted: systemic lupus erythematosus (13 papers); autoimmune conditions (4); idiopathic inflammatory myopathies (4); interstitial lung disease (3); antisynthetase syndrome (2); calcinosis (2); idiopathic pulmonary fibrosis (2); juvenile DM (2); autoimmune encephalitis (1); breast carcinoma (1); connective tissue diseases (1); COVID-19 (1); encephalitis (1); epilepsy (1); focal epilepsy (1); Hashimoto thyroiditis (1); hyperaldosteronism (1); Hyperkalemia (1); hypersensitivity pneumonitis (1); idiopathic interstitial pneumonia (1); juvenile idiopathic arthritis (1); kernicterus (1); lung carcinoma (1); lupus erythematosus (1); lymphoma (1); Mitral regurgitation (1); muscle atrophy (1); Myalgia (1); myonecrosis (1); nasopharyngeal carcinoma (1).
A further 19 diseases each share a sentence with NT5C1A in 1 paper.